ENSG00000277948
Gene: Miscellaneous RNA gene on chromosome 2 (175,092,401 to 175,092,587, reverse strand). Ensembl gene ENSG00000277948.
Homologues: Orthologues: mouse Gm56182 (64% identical).